CGAS (cyclic GMP-AMP synthase)
Diseases named in the same sentence as CGAS in open-access papers (continued):
Sharing a sentence is not in itself a finding about the gene and the disease.
progeria (4 papers, 2020 to 2024). "In general, our current results revealed a novel mechanism for senescence-associated phenotypes of postmitotic myofiber in progeria-aged mice, which involves increased cGAS-Sting activation caused by mitochondria damage, VDAC1 oligomerization, and mtDNA release." (PMID 39039044, 2024). "Our recent study of Z24−/− mice revealed the role of cytosolic ncDNA-induced cGAS-Sting innate immune response in mediating accelerated cellular senescence of muscle stem cells in progeria aging." (PMID 39039044, 2024). "We observed that increased cytoskeletal stiffness and RhoA activation in progeria cells were directly coupled with increased nuclear blebbing, Sun2 expression, and micronuclei‐induced cGAS‐Sting activation, part of the innate immune response." (PMID 32710480, 2020). "In our study, VBIT4 treatment of Z24−/− myofibers in vitro was effective in inhibiting mtDNA-induced cGAS-Sting activation and expression of SASP factors, suggesting that VDAC1 can be a novel molecular target for improving progeria aging-associated defective phenotypes." (PMID 39039044, 2024). "It has been shown that the cGAS-STING signalling is activated in HGPS cells and in a murine progeria model (likely due to DNA repair defect or replicative stress)." (PMID 33918867, 2021). "Although our recent study of Z24−/− mice revealed the critical role of cGAS-Sting innate immune pathway in mediating the senescence of progeria muscle stem cells, whether innate immune activation also plays a role in mediating atrophic phenotypes of progeria aged myofibers is not known." (PMID 39039044, 2024).
prostate adenocarcinoma (4 papers, 2021 to 2026). "The prostate adenocarcinoma PC3 cell line expressed both cGAS and STING." (PMID 41509453, 2026). "However, the prognostic roles and immune functions of cGAS-STING pathway-related genes in patients with prostate adenocarcinoma (PRAD) remain unclear." (PMID 36550819, 2022). "Most tumor tissues displayed a higher cGAS-STING score compared with their corresponding nontumor tissues, except for prostate adenocarcinoma (PRAD) and uterine corpus endometrial carcinoma (UCEC)." (PMID 35983076, 2022).
psoriasis (4 papers, 2015 to 2025). An autoimmune condition characterized by red, well-delineated plaques with silvery scales that are usually on the extensor surfaces and scalp. "In addition, we found that poly (dA:dT) induced type-I IFN production is dependent on RIG-I but not cGAS in psoriasis patients’ PBMCs." (PMID 25658361, 2015).
retinal degeneration (4 papers, 2022 to 2025). Degeneration of the retina. "Schematic summary of the mechanism underlying BRD4 inhibition on cGAS-STING signaling during retina degeneration." (PMID 35347235, 2022). "Mice were exposed to bright light to induce retinal degeneration, and the activation of cGAS-STING was determined by RNA-sequencing and molecular biology." (PMID 37217935, 2023). "We recently found the first-generation BET inhibitor JQ1 alleviated sodium iodate-induced retinal degeneration by suppressing cGAS-STING innate immunity." (PMID 37217935, 2023). "During the process of retinal degeneration, cytosolic DNA along with other cellular debris, remain at the site of degeneration, which can activate a cGAS-STING-mediated immune response." (PMID 36145721, 2022). "BRD4 was increased in injured retina and BRD4 inhibition ameliorates retina degeneration and inflammation, inhibits cGAS-STING activation, and promotes cytosolic DNA clearance." (PMID 35347235, 2022). "Indirect evidence for this was provided by a study of the cGAS-STING pathway in retinal degeneration." (PMID 36145721, 2022). "cGAS-STING activation was detected in oxidative stress-induced mouse retina degeneration, accompanied with cytosolic leakage of damaged DNA in photoreceptors." (PMID 35347235, 2022). "Here, we demonstrated activation of cGAS-STING promotes OS-induced retina degeneration and inflammation." (PMID 35347235, 2022). "Here, we have showed cytosolic DNA leakage in photoreceptor and activation of the cGAS-STING pathway in OS-induced retina degeneration." (PMID 35347235, 2022). "Together, cGAS-STING signaling was activated in OS-induced retina degeneration and retina aging." (PMID 35347235, 2022). "This study indicates targeted degradation of BET by dBET6 exerts neuroprotective effects by inhibiting cGAS-STING in reactive retinal macrophages/microglia, and is expected to become a new strategy for treatment of retinal degeneration." (PMID 37217935, 2023). "Our results have also revealed global activation of cGAS-STING signaling, and upregulation of STING in the reactive macrophages/microglia during pathogenesis of LD-induced retinal degeneration." (PMID 37217935, 2023). "We and others have recently shown that cGAS-STING signaling is aberrantly activated in retina and RPE of AMD patients, and contributes to RPE and retinal degenerations." (PMID 37217935, 2023). "Next, cGAS-STING signaling was investigated in an acute RPE and retina degeneration mouse model induced by oxidant sodium iodate (SI)." (PMID 35347235, 2022). "Moreover, the activation of Cyclic GMP-AMP Synthase–Stimulator of Interferon Genes (cGAS-STING) signaling, which is a key cytosolic DNA sensor system in innate immunity, was also detected in the context of oxidative stress-induced retinal degeneration." (PMID 40649951, 2025).
Sjogren syndrome (4 papers, 2022 to 2023). An autoimmune disorder in which immune cells attack and destroy the glands that produce tears and saliva. "In vivo, activation of the cGAS-STING pathway can mediate Sjogren’s syndrome-like pathological changes in salivary glands and lungs." (PMID 35812407, 2022). "Research on the cGAS-STING pathway in Sjogren’s syndrome is still in the preliminary stage, and more evidence is needed to prove its role in Sjogren’s syndrome, thus suggesting that the cGAS-STING pathway may become a hotspot for future studies on the innate immune response." (PMID 35812407, 2022). "A prominent role of cGAS in the development of Sjogren’s Syndrome (SS) would not be unexpected since this disease shares many similarities with SLE; this has been confirmed by a recent publication showing hypersensitivity to cGAS/STING activators in SS patients." (PMID 35406723, 2022).
squamous cell carcinoma (4 papers, 2022 to 2025). A carcinoma arising from squamous epithelial cells. "In this study we report that cisplatin exposure increases STING expression, activates the cGAS-STING pathway and induces an interferon response in epidermoid carcinoma NSCLC cells." (PMID 40445433, 2025). "TCGA data analysis of STING and cGAS in AC and SCC shows that low expression of STING in adenocarcinoma, but not squamous cell carcinoma, correlates with poor survival." (PMID 35099823, 2022).
steatosis (4 papers, 2024 to 2025). Increased lipid within the cytoplasm of cells. "To investigate whether JTTZF ameliorates hepatocyte steatosis and inflammation by regulating the cGAS‐STING pathway, we used C‐176, a STING inhibitor, to investigate the molecular mechanism of action of JTTZF." (PMID 41250907, 2025). "These mitochondrial defects activated the cGAS–STING–TBK1 inflammatory axis and contributed to steatosis, fibrosis, and hepatocellular injury." (PMID 41155556, 2025). "Genetically engineered probiotics like ZB183 have shown potential benefits; in a MASH murine model, Zbiotics downregulated the cGAS-STING pathway, reducing liver inflammation and steatosis and improving colonic health, indicating its potential as a novel therapeutic candidate." (PMID 40871398, 2025).
age (3 papers, 2020 to 2026). A temporal measurement of the time period elapsed since an identifiable point in the life cycle of an organism. "Furthermore, recent research highlights crosstalk between Yes-associated protein (YAP) transcriptional coactivator with a PDZ-binding domain (TAZ) and the cGAS-STING pathway as a key focus in age-related AS pathogenesis." (PMID 40351606, 2025). "Similarly, it is favorable that patients with immune system sickness, malignancy, age‐related ailments, and infections would all be able to benefit from focusing on the cGAS‐cGAMP‐STING pathway." (PMID 32195086, 2020).
amyloid (3 papers, 2023 to 2025). "On the contrary, other pathways such as GAS‐MerTK signaling, which is known to suppress neuroinflammation, were greatly diminished in amyloid pathology and were re‐established with cGAS deletion." (PMID 39908354, 2025). "Constitutive activation of the cGAS-STING pathway in human AD and aged mice were observed, and cgas deficient 5xFAD (cgas−/−; 5xFAD) mice presented a better cognitive behavior and reduced amyloid pathology." (PMID 37744399, 2023). "cGAS and STING were more highly expressed in ADLPAPP/PS1 mice than in AppNL-G-F mice at similar ages, with a pattern similar to that of amyloidosis." (PMID 39218977, 2024).
autoimmune hepatitis (3 papers, 2023 to 2025). Hepatitis caused by autoantibodies. "However, only a few documented instances exist of cGAS-STING signalling being implicated in autoimmune liver diseases." (PMID 39183465, 2024). "Using a model of autoimmune hepatitis induced by injection of the lectin concanavalin A, the authors demonstrate that NET induction resulted in cGAS-dependent stimulation of IFN-I response, suggesting that NETs also activate cGAS in vivo." (PMID 37187738, 2023). "Because the cGAS-STING pathway is central to both innate and adaptive immunity, it may participate in autoimmune liver disease." (PMID 39183465, 2024). "(2024) reported that trace element dyshomeostasis, specifically manganese overload, activates the cGAS-STING pathway, thereby mediating inflammation and exacerbating liver injury in a murine model of autoimmune hepatitis (AIH)." (PMID 41438738, 2025).
B cell lymphoma (3 papers, 2022 to 2025). "STAT3 inhibition also synergized with inducers of type I IFN, a downstream effector of the cGAS-STING pathway, to effectively inhibit B cell lymphoma growth, possibly by alleviating the suppressive effects of STAT3 on IRF7, IRF9, STAT1, and STAT2 expression." (PMID 40743845, 2025).
bone tumors (3 papers, 2021 to 2025). "In particular, we discuss recent findings on how aberrant cGAS-STING signaling contributes not only to chronic inflammatory bone loss but also to the tumor immune microenvironment in primary bone cancers and bone metastases." (PMID 41415288, 2025). "Compared to that of control tumors, TAMs in ASH1L-depleted bone tumors showed significant elevation in inflammation pathways, including IFN signaling, TNF signaling, IL-1/2 signaling, cGAS-STING, and antigen processing and presentation pathway." (PMID 40394007, 2025). "Future research should focus on delineating the spatiotemporal regulation of cGAS–STING signaling across different orthopedic conditions and bone tumors, elucidating its interplay with immune responses, bone metabolism, and disc homeostasis." (PMID 41415288, 2025). "In OS, activation of cGAS–STING can enhance antigen presentation and recruit T cells into the bone tumor microenvironment, providing a mechanistic basis for combinations with chemotherapy/radiotherapy or checkpoint blockade." (PMID 41415288, 2025).
chlamydial infection (3 papers, 2020 to 2026). "The cGAS-STING pathway is activated during chlamydial infection and plays a critical role in controlling Chlamydia trachomatis infection in the mouse lower genital tract." (PMID 42059376, 2026). "cGAS is required for IFN-β expression during chlamydial infection in multiple cell types, and murine and human studies indicate IFN-β compromises resolution of chlamydial infection and exacerbates pathology." (PMID 36248887, 2022).
cholangiocarcinoma (3 papers, 2024 to 2026). A carcinoma that arises from the intrahepatic biliary tree (intrahepatic cholangiocarcinoma) or from the junction, or adjacent to the junction, of the right and left hepatic ducts (hilar cholangiocarcinoma). "Immunohistochemical results revealed that the expression of RIG-I, MAVS, cGAS, IRF3, MDA5, IFIT2, and IRF7 was significantly higher in liver tissue slices from patients with cholangiocarcinoma than in the control group." (PMID 38817870, 2024). "However, the information regarding the cGAS-STING pathway in cholangiocarcinoma (CCA) is limited." (PMID 40786100, 2025).
cystic fibrosis (3 papers, 2023 to 2025). Autosomal recessive disorder caused by pathogenic variants in the CFTR gene (cystic fibrosis transmembrane conductance regulator), which encodes a chloride and bicarbonate channel expressed in epithelial cells, and follow the diagnosis criteria. "Our work indicates that the cGAS/STING pathway integrity is crucial in the Cystic Fibrosis response against pathogens and that the restoration of the pathway by 2’, 3’ cGAMP could be exploited as a possible new target for the symptomatic treatment of the disease." (PMID 36923406, 2023).
dementia (3 papers, 2022 to 2025). Loss of intellectual abilities interfering with an individual's social and occupational functions. "This review focuses on emerging research exploring the cGAS-STING pathway’s role in dementia, examining its potential as a diagnostic and therapeutic target." (PMID 41300248, 2025). "Accordingly, this review summarizes current understanding of neuroinflammation and highlights emerging evidence for the cGAS-STING pathway as a diagnostic and therapeutic target in dementia." (PMID 41300248, 2025). "The connection between this pathway and major risk factors for dementia such as APOE, TREM2, c9orf72 highlights cGAS-STING pathway as a common convergence point in neuro-immune axis, affecting disease onset and progression." (PMID 41300248, 2025). "In summary, the cGAS-STING pathway plays a crucial role in mediating neuroinflammation across various dementia including AD, VaD, PD and FTD." (PMID 41300248, 2025). "In the context of neurodegenerative diseases, such as AD and other types of dementia, the activation of the cGAS-STING pathway has gained increasing attention as a key mediator of neuroinflammation." (PMID 41300248, 2025). "In alignment with our findings of early cGAS/STING activation, cGAS/STING is implicated in frank dementia, such as AD/ADRD." (PMID 36248795, 2022). "Although no clinically approved inhibitors currently exist, continued research into selective and tunable modulators of the cGAS–STING pathway offers a promising avenue for developing disease-modifying therapies in dementia and related neurodegenerative disorders." (PMID 41300248, 2025). "Furthermore, delineating the dynamic changes and dual roles of the cGAS‐STING pathway across the AD continuum, from preclinical to dementia stages, will be critical for founding personalized immunomodulatory therapies." (PMID 41376208, 2025). "While much remains to be understood about the precise mechanisms by which cGAS-STING contributes to neurodegeneration, the development of inhibitors targeting this pathway has already demonstrated preclinical success in alleviating neuroinflammation and pathology in dementia animal models." (PMID 41300248, 2025).
dengue (3 papers, 2022 to 2025). "Moreover, virus-mediated autophagic degradation of cGAS has also been described for other RNA viruses, such as dengue and Chikungunya." (PMID 39836220, 2025). "Similarly, cGAS and the stimulator of interferon genes play a role in restricting the infection of several RNA viruses, such as Dengue, Sendai, vesicular stomatitis, and the West Nile virus." (PMID 39127175, 2024). "In the infected cells, dengue circumvents antiviral signaling at multiple levels: through evasion of viral RNA sensing, interference of retinoic acid-inducible gene (RIG-I) and mitochondrial antiviral-signaling (MAVS) protein and cGAS/STING pathways, and interference with interferon signaling." (PMID 36197108, 2022).
disc degeneration (3 papers, 2022 to 2025). "Collectively, targeting cGAS-STING pathway at the early stage of IVD (endplate or annulus fibrosus) injury may halt accelerated disc degeneration, probably by regional alleviation of cellular senescence and SASP-based inflammation." (PMID 39034400, 2024). "Recent work has demonstrated cGAS-STING activation in a LPS vertebral injury-induced disc degeneration model; however, this activation was only achieved with the inflammatory stimulus of LPS and by breaching the integrity of the EP, enabling immune cell infiltration into the disc compartment." (PMID 35769461, 2022). "Overall, the analyses of the vertebral columns of N153S and STING-/- mice indicate that the cGAS-STING pathway is not a major contributor to SASP induction and disc degeneration but may play a small role in the maintenance of trabecular bone in the vertebrae." (PMID 35769461, 2022).
Fanconi anemia (3 papers, 2019 to 2023). Fanconi anemia (FA) is a hereditary DNA repair disorder characterized by progressive pancytopenia with bone marrow failure, variable congenital malformations and predisposition to develop hematological or solid tumors. "Also, intrinsic deactivation of the DDR by genetic defects, as in rare DNA repair deficiency syndromes like Fanconi anemia (FA) or BRCAness in hereditary breast and ovarian cancer, triggers cGAS/STING signaling and inflammatory processes through genomic instability." (PMID 37834346, 2023). "To address this, we tested MHF, a component of the Fanconi anemia (FA) core complex that binds dsDNA with a similar affinity as cGAS alongside the latter." (PMID 31544964, 2019).
fungal keratitis (3 papers, 2023 to 2025). "A. fumigatus also elicits inflammatory responses in the host responsible for fungal keratitis via cGAS and STING." (PMID 39803513, 2025). "Available data suggests that miRNAs, Beclin 1, and the cGAS-STING pathways may play key roles in mediating autophagy during fungal keratitis." (PMID 37153108, 2023).
herpes simplex encephalitis (3 papers, 2020 to 2023). Herpes simplex virus encephalitis (HSE) is caused by the infection of the central nervous system by Herpes simplex virus (HSV) that could have a devastating clinical course and a potentially fatal outcome particularly with delay or lack of treatment. "cGAS deficiency also led to impaired IFN expression in microglia, thus resulting in the susceptibility of the mice to herpes simplex encephalitis (HSE) upon ocular infection." (PMID 33584700, 2020). "The cGAS-STING pathway is essential to control HSV-1 brain infection as shown with mouse models and human genetic studies (see “Herpes simplex encephalitis”)." (PMID 34676800, 2021).
keratitis (3 papers, 2022 to 2025). A corneal disease that is characterized by inflammation of the cornea. "Furthermore, the cGAS-STING signaling pathway has been implicated in the inflammatory response of Aspergillus fumigatus keratitis." (PMID 41459537, 2025). "Inhibition of cGAS with the RU.521 compound reduces the severity of keratitis in mouse corneas, highlighting the detrimental role of the cGAS–STING pathway in this infection model, like in candidiasis." (PMID 41249509, 2025). "A recent study demonstrated that A. fumigatus keratitis activates the cGAS–STING pathway, as evidenced by increased expression of cGAS, STING, and TBK1 in both human corneal epithelial cells and mouse corneas." (PMID 41249509, 2025). "However, more studies are required to examine the level of cGAS-STING signaling during keratitis caused by the ΔwspF and plac-yhjH strains, to assess whether intracellular c-di-GMP contents in P. aeruginosa play a role in modulating the host cGAS-STING signaling activity." (PMID 35913171, 2022). "This phenomenon may be attributed to the observation that the inhibition of cGAS/STING signaling has been demonstrated to promote NLRP3 inflammasome activation and pyroptosis, consequently exacerbating keratitis." (PMID 41459537, 2025).